CSF1R (colony stimulating factor 1 receptor)
Diseases named in the same sentence as CSF1R in open-access papers (continued):
Sharing a sentence is not in itself a finding about the gene and the disease.
Hodgkins lymphoma (26 papers, 2013 to 2025). A heterogeneous group of malignant lymphoid neoplasms of B-cell origin characterized histologically by the presence of Hodgkin and Reed-Sternberg (HRS) cells in the vast majority of cases. "Numerous studies have reported that high expression of CSF-1 or its receptor CSF-1R is associated with poor prognosis in malignant tumors, such as in breast cancer and Hodgkin’s lymphoma." (PMID 34178692, 2021). "LTR-driven oncogene activation has been reported in multiple cancers, with a notable example in Hodgkin’s lymphoma where an LTR element contributes an alternate promoter causing ectopic activation of the CSF1R oncogene." (PMID 31061680, 2019). "In Hodgkin lymphoma patients treated with standard chemotherapy, higher CSF1R expression was associated with shorter survival." (PMID 29872489, 2018). "For example, a demethylated copy of MaLR LTR can act as an alternative promoter to transcriptionally derepress the gene CSF1R, encoding colony stimulating factor-1 receptor, which is linked with survival of the Hodgkin's lymphoma cells." (PMID 28642863, 2017). "The prominent demethylation of CpG elements was found in the LTR region upstream CSF1R in several of Hodgkin’s lymphoma cell lines, suggesting that epigenetic alterations activate the LTR promoter activity for aberrant CSF1R expression." (PMID 38136578, 2023). "This is well demonstrated by an upstream MaLR (THE1B) LTR sequence providing an alternative promoter to CSF1R in Hodgkin’s lymphoma, a B cell cancer." (PMID 33971937, 2021). "For example, hypomethylation in LTR promoters is able to induce carcinogenesis in B cell-derived Hodgkin’s lymphoma by deregulating the expression of the colony-stimulating factor 1 receptor (CSF1R), a proto-oncogene." (PMID 32640516, 2020). "The first study reported activation of the colony stimulating factor 1 receptor (CSF1R) gene in Hodgkin’s lymphoma and the second reported activation of the fatty acid binding protein 7 (FABP7) gene in diffuse large B-cell lymphoma." (PMID 25821520, 2015). "In cHL, CSF1R+ TAMs were most frequent in the nodular sclerosis and mixed cellularity subtypes, with lower frequencies observed in lymphocyte-rich cHL." (PMID 26066800, 2015). "For instance, Hodgkin’s lymphoma has been shown to arise from aberrant transcription of the colony-stimulating factor 1 receptor (CSF1R) gene driven by an internal LTR element known as THE1B." (PMID 24946810, 2014). "Two prominent examples of the clinically significant HERV/LTR activation have been reported: CSF1R oncogene activation by a MaLR LTR in Hodgkin’s lymphoma and RCC-specific novel HERV-E antigen expression facilitating the immunotherapy." (PMID 24062987, 2013). "For example, Hodgkin’s lymphoma cells can aberrantly express CSF-1R and are sensitive to CSF-1R inhibitor therapy; thus, the CSF-1R pathway could be a potential target for the treatment of Hodgkin’s lymphoma." (PMID 41315192, 2025). "CSF1R expression is critical for the survival of B-cell- derived Hodgkin’s lymphoma cells." (PMID 41459148, 2025). "Several safety studies of CSF1R inhibition in healthy subjects, patients with rheumatoid arthritis, and patients with advanced or metastatic cancers, including giant cell tumors, glioblastoma, and Hodgkin lymphoma, have been reported." (PMID 32801364, 2020). "In Hodgkin’s lymphoma aberrant activation of an LTR belonging to the THE1B subfamily of mammalian apparent LTR retrotransposons (MaLRs) promotes transcriptional activation of colony-stimulating factor 1 receptor (CSF1R) which is essential for tumor survival." (PMID 25927889, 2015). "Hypomethylation often affects HERV-derived solo LTRs that function as alternate promoters, for example the HERV-derived LTR is hypomethylated in B cell-derived Hodgkin’s lymphoma and is responsible for deregulated expression of the colony-stimulating factor 1 receptor (CSF1R), a protooncogene." (PMID 24066280, 2013).
Hodgkins lymphoma (continued). "An example of such a case was reported in Hodgkin’s Lymphoma, where the THE1B retrotransposon acts as an alternative promoter for the colony-stimulating factor 1 receptor (CSF1R) proto-oncogene." (PMID 40328728, 2025). "In Hodgkin’s lymphoma, THE1B LTR hypomethylation drives lineage-inappropriate expression of the colony-stimulating factor 1 receptor (CSF1R), which is essential for tumor survival." (PMID 41315192, 2025). "CSF1R inhibitors have already been studied in several human diseases and JNJ-40346527 proved ineffective in Phase 2 trials for rheumatoid arthritis, Crohn’s disease (Provention Bio press release, 2019), and Hodgkin’s lymphoma." (PMID 37332353, 2023). "Other small molecule CSF-1R inhibitors include ARRY-382, PLX7486, BLZ945 and JNJ-40346527 (edicotinib), and all are currently being evaluated in clinical trials for treatment of Hodgkin lymphoma (cHL)." (PMID 37114134, 2023). "A well-documented examples is expression of colony-stimulating factor 1 receptor (CSF1R), which in healthy haematopoietic cells is driven by its own promoter, whereas in Hodgkin's lymphoma cells it is driven by an upstream LTR, promoting survival of cancer B cells by excess CSF1R expression." (PMID 28893944, 2017). "Furthermore, in Hodgkin's lymphoma cells, a THE1B-MaLR element provides an alternative promoter for the CSF1R proto-oncogene and de-repression of THE1B elements is widespread." (PMID 24278031, 2013). "In Hodgkin’s lymphoma cells, CSF1R is upregulated, despite absence of PU.1." (PMID 33971937, 2021).
leukemia (26 papers, 2015 to 2026). A malignant (clonal) hematologic disorder, involving hematopoietic stem cells and characterized by the presence of primitive or atypical myeloid or lymphoid cells in the bone marrow and the blood. "Similar to other leukemia-associated CSF1R fusions, G3BP1::CSF1R retains an amino-terminal dimerization domain termed nuclear transport factor 2-like (NTF2L) from the partner fused to the tyrosine kinase domain of CSF1R." (PMID 37002311, 2023). "Nevertheless, inappropriate expression of CSF1R has been associated with several malignancies, including breast cancer, prostate cancer, ovarian cancer, leukemias, and Hodgkin’s lymphoma." (PMID 33842370, 2021). "Additionally, the report that CSF1R was only expressed in AML LSCs (leukemic stem cells) but not in HSCs (normal hematopoietic stem cells) further implicated CSF1R as an interesting AML target with less on-target off-leukemia toxicity." (PMID 38641704, 2024). "In cases of chronic lymphocytic leukemia (CLL), blocking the signaling pathway of the colony-stimulating factor 1 receptor (CSF1R) or using clodronate liposomes to kill macrophages can effectively hinder the growth of the leukemia." (PMID 41041337, 2025). "RNA-seq analysis of A485-treated K/C-III leukemia cells further revealed significant downregulation of key hematopoietic factors, including Hoxa9, Hoxa10, Meis1, Cd34, c-Kit, and Csf1r." (PMID 40830799, 2025). "CSF‐1R, the surface receptor that binds M‐CSF, is expressed by some leukemia cells, while CSF‐1R‐expressing resident macrophages in bone marrow are requested for the persistent engraftment of long‐term reconstituting hematopoietic stem cells." (PMID 37697915, 2023). "We suggest a novel approach for eliminating leukemic cells directly and attacking the leukemia-supporting surrounding stroma by inhibiting CSF1R signaling." (PMID 33842370, 2021). "Other CSF-1R Inhibitors including imatinib, dasatinib and bosutinib are approved for use in patients with leukemia and other types of cancer." (PMID 34654458, 2021). "Indeed, MOZ fusion proteins trigger strong CSF-1R transcription, which is dependent on PU.1 transcription factors, and leads to the constitutive expression of the CSF-1R in leukemia stem cells, thereby inducing AML." (PMID 39457693, 2024). "Signaling through CSF-1R, the major receptor of IL-34, is vital for the differentiation and survival of mononuclear phagocytes; and macrophages play important roles in malignancies including leukemia." (PMID 37149693, 2023). "Summary of CSF1R targeted therapies for leukemias in clinical trials (2020)." (PMID 33842370, 2021). "The signalling between macrophages and leukaemia cells can be abrogated by CSF‐1R inhibition." (PMID 33037771, 2020). "Finally, CSF1R inhibition on a KMT2A::MLLT3+ paediatric leukaemia cell line resulted in significant cell death, suggesting that CSF1R could be therapeutically targeted in these patients." (PMID 41545699, 2026). "Moreover, CLL could induce polarization of M2 macrophages via the colony-stimulating factor-1 (CSF1)-CSF1R pathway, and blocking CSF1R signal transduction can reduce the leukemia cell load." (PMID 33553181, 2021). "In line with their leukaemia-propagating properties, KMT2A::MLLT3 + CSF1R+ LMPPs possess a stem cell-like and myeloid-biased expression signature and require autophagy to expand and form blast-like colonies in methylcellulose." (PMID 41545699, 2026). "Interestingly, the delivery in this mouse model of anti-CSF1R antibodies, which depletes monocytes by inducing apoptosis and blocking their differentiation to macrophages, along with the tyrosine kinase inhibitor nilotinib, significantly increased the overall survival of leukemia-transplanted mice." (PMID 33922612, 2021). "Using a highly selective CSF‐1R inhibitor, BLZ945, we found that the pharmacologic inhibition of CSF‐1R decreased the abundance of LAMs in BM and spleen of leukaemia mice." (PMID 33037771, 2020).
leukemia (continued). "In vivo, combination treatment of CSF‐1R inhibitor and vincristine (VCR) dramatically increased the survival of T‐ALL mice and delayed leukaemia progression compared with VCR monotherapy." (PMID 33037771, 2020). "AI-10-49 is of particular interest for treatment of (inv16) AML as it inhibits RUNX1 binding to CSF1R, RUNX3 and CEBPa promoter targets and also strongly increases mice survival in CBFβ-MYH11 murine leukemia cell models by reducing leukemia burden." (PMID 29921764, 2018). "We propose enhancing this strategy in CLL patients through combination drug approaches by simultaneously giving CSF1R inhibitors, which target NLCs, with BTK and/or PI3Kδ inhibitors as well as other agents, which target the leukemia cells themselves." (PMID 29872489, 2018). "We used imatinib, a small molecule tyrosine kinase inhibitor that was originally developed to inhibit the BCR-ABL fusion protein in leukemia but also inhibits c-Kit, PDGF receptors, and CSF1R and is being investigated as a possible chemotherapy for metastatic melanoma." (PMID 32450888, 2020). "Interestingly, for one patient specimen unable to produce a significant number of NLCs even in the untreated condition, the CSF1R inhibitors did not decrease viability, suggesting that their efficacy is dependent on the presence and activity of NLCs within the leukemia." (PMID 29872489, 2018).
tenosynovial giant cell tumor (26 papers, 2018 to 2025). A tumor usually arising in the synovium of joints, bursa or tendon sheath. "The Colony-Stimulating Factor-1 Receptor (CSF-1R) tyrosine kinase plays a crucial role in regulating macrophage and osteoclast production and has been implicated in tenosynovial giant cell tumor (TGCT) a rare, locally aggressive neoplasm of the joint or tendon sheath." (PMID 38886570, 2024). "In addition, patients with tenosynovial giant cell tumors caused by genetic translocation-induced CSF1 overexpression have shown clinical efficacy when treated with the CSF-1R inhibitor pexidartinib, with an ORR of 39%." (PMID 37545490, 2023). "Pexidartinib is a colony-stimulating factor-1 receptor inhibitor approved in the United States for treatment of adult patients with symptomatic tenosynovial giant cell tumor (TGCT) associated with severe morbidity or functional limitations and not amenable to improvement with surgery." (PMID 37805596, 2023). "CSF-1R inhibitor tyrosine kinase pexidartinib is the first approved systemic therapy for patients with tenosynovial giant cell tumors; however, it may cause potentially life-threatening mixed or cholestatic hepatotoxicity." (PMID 36143947, 2022). "Pexidartinib, a clinically approved CSF1R inhibitor for the treatment of tenosynovial giant cell tumors, served as a positive control and is significantly more potent with an IC50 of 26 nmol/L." (PMID 40018846, 2025). "So far, the FDA has approved two CSF-1R inhibitors for patients with tenosynovial giant cell tumors, a tumor type characterized by chromosomal translocations of the CSF-1 gene, leading to aberrant CSF-1 expression." (PMID 40646332, 2025). "CSF1R is overexpressed in macrophage-rich tumors such as tenosynovial giant cell tumor (TGCT), which plays a key role in the recruitment and proliferation of tumor-associated macrophages." (PMID 41041285, 2025). "The CSF-1R inhibitor pexidartinib shrank tumor size and improved symptoms in patients with tenosynovial giant cell tumor (TGCT), with encouraging results in the phase III clinical study (NCT02371369) of CSF1/CSF1R-targeted therapy for benign diffuse TGCT." (PMID 39065562, 2024). "Pexidartinib (PEX,TURALIO), a selective and potent inhibitor ofthe macrophage colony-stimulating factor-1 receptor, has been approvedfor the treatment of tenosynovial giant cell tumor." (PMID 37531179, 2023). "Pexidartinib is an oral TKI with selective inhibition of CSF1R, which has been approved by the FDA for treatment of adult patients with symptomatic tenosynovial giant cell tumor (TSGCT) that is associated with severe morbidity or functional limitations and not responsive to improvement with surgery." (PMID 40943476, 2025). "Importantly, CSF1R inhibitors are already an approved class of drug for the treatment of Tenosynovial giant cell tumor, and recent work has established the viability of a CSF1R inhibition-based treatment paradigm for Sandhoff disease, further emphasizing the translatability of this strategy." (PMID 40866328, 2025). "Pexidartinib, an oral selective colony-stimulating factor 1 receptor (CSF1R) inhibitor, is the only systemic therapy approved by the U.S. Food and Drug Administration (FDA) for tenosynovial giant cell tumor (TGCT)." (PMID 40900794, 2025). "PLX3397, an orally available inhibitor of CSF-1R and KIT, given daily, has received FDA approval for treatment of tenosynovial giant cell tumor." (PMID 40760255, 2025). "Several clinically investigational CSF1R inhibitors (CSF1Ri), either TKIs or antibodies, are being developed, but with limited success, except for tenosynovial giant cell tumors (TGCT), where CSF1R alteration is the sole driver of the disease." (PMID 38641704, 2024). "Pexidartinib (PLX3397), a CSF1R inhibitor, was approved by Food and Drug Administration (FDA) for the treatment of tenosynovial giant cell tumors." (PMID 37361567, 2023).
tenosynovial giant cell tumor (continued). "CSF1R-targeting agents are generally well-tolerated in the clinic, and the multi-TKI CSF1R inhibitor Pexidartinib is FDA-approved to treat tenosynovial giant-cell tumor." (PMID 35273619, 2022). "This is of potential interest since tenosynovial giant cell tumors (TGCTs) are characterized by rearrangements of CSF1, which is a ligand for CSF1R." (PMID 34888523, 2021). "Pexidartinib (Turalio), which inhibits the colony stimulating factor 1 receptor (CSF1R), is used for the treatment of symptomatic tenosynovial giant cell tumor (TGCT)." (PMID 34071280, 2021). "While clinical trials of small molecule CSF1R inhibitors and CSF1/CSF1R antibodies have been conducted in various types of cancer, a single reagent, PLX3397, has been clinically approved only for tenosynovial giant cell tumor (TGCT)." (PMID 39782686, 2025).
cognitive decline (23 papers, 2016 to 2026). "HDLS is a hereditary cerebral white matter degenerative disease caused by mutations of CSF1R and results in personality changes, followed by cognitive decline and motor impairment, particularly affecting the gait." (PMID 31093799, 2019). "Genetic studies that included a search for the commoner mutations causing cognitive decline revealed three patients with mutations; there were pointers to the correct diagnosis in all three (C9orf72 and CSF1R) on neurophysiology testing and MRI." (PMID 29142140, 2018). "Mutations of CSF1R cause inherited diffuse white matter encephalopathy with spheroids pathology, an autosomal dominant neurodegenerative disorder presenting with such clinical features as parkinsonism, cognitive decline, and personality and behavioral changes." (PMID 31554150, 2019). "CSF1R-related disorder (CSF1R-RD) is a rare autosomal dominant neurodegenerative disease characterized by cognitive decline, motor dysfunction, psychiatric symptoms, and white matter abnormalities." (PMID 41820324, 2026). "As all cases with BANDDOS with speech disturbances had accompanying cognitive decline or developmental delay, the multifaceted nature of speech dysfunction, as seen in CSF1R-ALSP, is most likely." (PMID 37349768, 2023). "In one report, CSF1R inhibitors increased the number of dystrophic neurites, while in other studies they reduced neuritic plaques and cognitive decline." (PMID 37332353, 2023). "Our data suggest a protective effect of CSF1R gene deletion to prevent cognitive decline in APP cKO mice." (PMID 33402196, 2021). "Conversely, Csf1r+/− mice can survive during adulthood period but then develop abnormal symptoms including cognitive decline and depression with anxiety-like behavior." (PMID 33287883, 2020). "Additionally, in rodents, depleting microglia by inhibiting the colony-stimulating factor 1 receptor (CSF1R) protects against post-operative cognitive decline via an anti-inflammatory mechanism." (PMID 39463449, 2025). "Single-cell RNA sequencing analysis showed that the cluster 9 was identified as microglia based on a higher expression of its specific marker IBA1and CSF1R in GD model mice suggesting that microglia was likely involved in the pathophysiological process of GD-related cognitive decline." (PMID 37740205, 2023). "Deletion of CSF1R in APPSwe/PS1AD mice delayed cognitive decline." (PMID 37108258, 2023). "We have also shown that cognitive decline is delayed in CSF1R-deleted mice." (PMID 33402196, 2021). "However, growing evidence has shown recently that CSF1R inhibition could also prevent cognitive decline and amyloid deposition." (PMID 33402196, 2021). "Therefore, to specifically study the role of SE-induced microgliosis on cognitive decline we focused on the colony-stimulating factor 1 receptor (CSF1R) because CSF1R was identified by the computational casual reasoning analytical framework for target discovery as a potential anti-epileptic target." (PMID 34149593, 2021). "Besides, many patients have typical ALSP clinical manifestations, including progressive cognitive decline, motor impairment, and mental behavioral abnormalities, but no CSF1R mutation." (PMID 34955818, 2021). "Mice with CSF1R ± monogenic mutation are viable, fertile, and without skeletal abnormalities, but then may present cognitive decline, depression, and anxiety." (PMID 34955818, 2021). "Modulating microglial function through colony-stimulating factor 1 receptor (CSF1R) inhibitors, such as PLX3397, has been shown to shift microglia toward a homeostatic phenotype, reducing neuroinflammation and cognitive decline in preclinical models." (PMID 40584220, 2025). "The relationships between the observed correlations of diet and the CSF1R, IGF1R, and PINK1 expression with regard to cognitive decline are less clear." (PMID 36771351, 2023).
cognitive decline (continued). "Specific inhibitors of CSF1R target and purge 99% microglia in the CNS and cross the blood-brain barrier, but neither mouse abnormal behavior nor cognitive decline was observed." (PMID 34955818, 2021).